CRP (C-reactive protein)
Diseases named in the same sentence as CRP in open-access papers (continued):
Sharing a sentence is not in itself a finding about the gene and the disease.
lymphopenia (continued). "In a meta-analysis study, lymphopenia, thrombocytopenia and high CRP, LDH and D-dimer values ​​were found to be associated with advanced disease." (PMID 35858851, 2022). "The combination of C-reactive protein ≥ 21 mg/L, hemoglobin < 11.0 g/dL, and lymphopenia < 1500 mm3 on hospital admission increased the risk of O2 use by 4.97-times." (PMID 35767901, 2022). "Studies have found that advanced age, high APACHE II score, lymphopenia, high lactate dehydrogenase, and C-reactive protein are associated with poor prognosis." (PMID 36292251, 2022). "This study revealed that elevated levels of d‐Dimer, serum ferritin, CRP, HR, lower SpO2%, and lymphopenia aid in the risk of COVID‐19 patients' assessment and adequate management." (PMID 35894709, 2022). "Chronic obstructive pulmonary disease, immunosuppression, radiological abnormalities, respiratory rate, lymphopenia, lactate dehydrogenase and C-reactive protein at admission were associated with RF." (PMID 36419130, 2022). "Severe disease was strongly associated with fever, cough, pneumonia, lymphopenia, increased levels of C-reactive protein (CRP), aspartate aminotransferase (AST) and alanine aminotransferase (ALT) activity, older age and male gender." (PMID 36583110, 2022). "Factors associated with infection severity were CRP > 100 mg/L (OR: 2.51, CI 95%: (1.40–3.71), p < 0.001) and lymphopenia < 800/mm3 (OR: 2.15, CI 95%: (1.42–3.27), p < 0.001)." (PMID 35407409, 2022). "Abnormal elevations of CRP, ferritin, procalcitonin, NT proBNP, neutrophil, and platelet counts, and lymphocytopenia were significantly associated with the risk of death, with procalcitonin and NT proBNP as the strongest predictors (aOR > 2)." (PMID 36224551, 2022). "Higher severity scores were associated with positive PCR tests, lymphopenia, and increased serum CRP, d-dimer, and ferritin levels." (PMID 36714121, 2022). "The mortality risk was associated with age, LDH, C‐reactive protein (CRP), D‐dimer, and lymphopenia in patients with comorbidities." (PMID 33112011, 2021). "Hyper-inflammatory immune responses with elevated CRP, neutrophilia, and lymphopenia are associated with a severe disease and a worse outcome." (PMID 33850271, 2021). "The data from this larger AAV cohort reconfirmed our previous finding, that active AAV is associated with naïve lymphopenia, and this effect is stronger if CRP was raised (i.e., ≥10 mg/L; p = 0.031)." (PMID 35095887, 2021). "A clinical presentation characterized by abdominal pain, lymphopenia, and increased C-reactive protein and ferritin levels was associated with a 9- to 30-fold increased probability of severe GI outcomes." (PMID 34928354, 2021). "MIS-C is associated with more severe lymphopenia, higher levels of the inflammatory markers C-reactive protein and ferritin, and lower platelet counts compared to Kawasaki disease." (PMID 34440163, 2021). "Hyperinflammatory immune responses with elevated CRP levels, neutrophilia, and lymphopenia are associated with severe disease and a worse outcome." (PMID 33850271, 2021). "Previous comorbidities required organic systemic therapy use, lymphopenia, and elevated D-dimer, and CRP levels were associated with increased AKI development risk." (PMID 34150790, 2021). "In general population studies, COVID-19 disease mortality was associated with lymphopenia, thrombocytopenia, and elevated CRP levels." (PMID 33446135, 2021). "Inflammatory markers such as high C-reactive protein (CRP) levels, lymphopenia, and elevated neutrophil counts are associated with a worse outcome." (PMID 33850271, 2021). "Liu et al14 have observed that lymphopenia was associated with prolonged hospitalization in COVID‐19 patients, whereas serum CRP and lymphocyte count were associated with adverse outcomes." (PMID 32644215, 2021).
lymphopenia (continued). "We found a prevalence of M1 polarized macrophage with a M1/M2 ratio of 3.1, which was parallel with our previous findings in advanced ovarian cancer patients, associated with high circulating levels of CRP, IL-6, and ferritin, as well as lymphopenia." (PMID 33550983, 2021). "The data from Cox proportional hazards regression analysis revealed that the mortality risk was associated with age, LDH, CRP, D‐dimer, and lymphopenia in cases with comorbidities." (PMID 33112011, 2021). "A previous analysis identified that lymphopenia, elevated CRP, and elevated creatinine are associated with organ injury and a higher risk of death." (PMID 34685377, 2021). "A clinical frailty score ≥5, severe lymphopenia, cumulative comorbidities and high CRP was associated with a higher mortality rate." (PMID 33043852, 2021). "This group found that renal involvement was associated with a greater elevation of CRP, ferritin, and procalcitonin, with greater lymphopenia and left ventricular dysfunction." (PMID 34794410, 2021). "Leukopenia, lymphopenia, thrombocytopenia, and elevated C-reactive protein (CRP) levels were identified as risk factors for severe cases." (PMID 33015110, 2020). "The calculated Pearson correlation showed once again the strong and clinically significant correlation between elevated CRP and lung lesions, and the association between the severity of the disease/patients age and lymphopenia." (PMID 32668763, 2020). "All this evidence justifies the laboratory pattern of neutrophilia and lymphopenia associated with an increase in the serological values of IL-6 and C reactive protein (CRP) commonly found in infected patients." (PMID 32560340, 2020). "A more modest interaction was observed between CRP level and ALC quintiles (P = .04) favoring intensification of CRP level–related risk in those with lymphopenia (eFigure 3 in the Supplement)." (PMID 31790569, 2019). "For clinical reference, the diagnostic performance of NLCR and lymphocytopenia for severe disease was compared to that of the classic biomarker serum CRP using receiver operating characteristic (ROC) analysis." (PMID 23506136, 2013). "CRP, as a key acute-phase reactant, has been implicated in endothelial dysfunction and vascular wall instability, whereas hypoalbuminemia and lymphopenia reflect impaired antioxidant capacity, disruption of capillary integrity, and reduced cellular immune competence." (PMID 41602960, 2026). "Elevated CRP and low albumin levels denote a catabolic, pro-inflammatory state that may predispose to procedural complications, while lymphopenia reflects immune suppression and increased infection risk." (PMID 41470144, 2025). "Furthermore, we have recently reported that both elevated CRP levels and lymphopenia are associated with indeterminate QFT Gold Plus results in a large cohort of predominantly healthy children and adolescents." (PMID 36335186, 2023). "A report in Wuhan, China, retrospectively evaluated a cohort of infected cases and initiated that high ferritin levels, along with several further biomarkers such as CRP, neutrophilia, lymphocytopenia, and D-dimer, LDH, were markedly linked with a greater risk of developing ARDS." (PMID 37754237, 2023). "Poorer survival outcomes in NPC have been linked to higher CRP levels and severe lymphopenia risks." (PMID 37545573, 2023). "Furthermore, the combination of CRP ≥ 21 mg/L with hemoglobin < 11.0 g/dL and lymphopenia < 1500 mm3 increased the risk of supplemental O2 almost fivefold." (PMID 35767901, 2022). "In univariate analysis, the factors associated with the severity of the infection were CRP > 100 mg/L (OR: 2.65, 95% CI: (1.98–3.56), p < 0.001), lymphopenia < 800/mm3 (OR: 1.70, 95% CI: (1.27–2.27, p < 0.001), and negative ∆L-H24 (OR: 2.03, 95% CI: (1.48–2.78); p < 0.001)." (PMID 35407409, 2022).
lymphopenia (continued). "The LDH, CRP, and lymphopenia were previously associated with COVID‐19 mortality, especially in Chinese patients where a tree‐based classifier (XGBoost) that included all three of these biomarkers achieved greater than 90% accuracy in predicting death in the independent validation cohort." (PMID 35313387, 2022). "The lower levels of PaO2/FIO2, when associated with lymphopenia, higher levels of C-reactive protein and lactate dehydrogenase, and higher chest tomography scores may also predict prolonged hospitalization." (PMID 35956189, 2022). "Additionally, male sex, immunosuppression and inflammatory markers such as C-reactive protein, neutrophilia and lymphopenia are associated with the severity of the disease and death." (PMID 35807129, 2022). "Over the past decade, several observational studies have demonstrated that increased inflammatory markers (elevated WBC, tumor necrosis factor-α, interleukin-6, and C-reactive protein [CRP]) and lymphopenia are associated with both cardiovascular and all-cause mortality among hemodialysis patients." (PMID 36644346, 2022). "In multivariate analysis, the factors associated with the severity of the infection were CRP > 100 mg/L (OR: 2.51, 95% CI: (1.70–3.71), p < 0.001), lymphopenia < 800/mm3 (OR: 2.15, 95% CI: (1.42–3.27, p < 0.001), and negative ∆L-H24 (OR: 3.16, 95% CI: (2.11–4.75); p < 0.001)." (PMID 35407409, 2022). "Of note, there were significant sex differences (p interaction < 0.05) in the association of CRP, ferritin, NT proBNP, lymphopenia with increased neutrophils, and COVID-19 death, where the abnormal levels of biomarkers showed a more pronounced effect in women than in men." (PMID 36224551, 2022). "However, tachypnea, hypoxia, lymphopenia, and high plasma levels of C-reactive protein and lactate dehydrogenase were associated with higher mortality." (PMID 36629525, 2022). "Thirdly, higher levels of inflammatory markers such as CRP were associated with lymphopenia." (PMID 35095756, 2021). "Viral co-infections are additional risk factors for disease progression and high CRP levels and lymphopenia may be predictive markers of severe clinical pictures." (PMID 33796491, 2021). "These values would be in line with our results, which showed higher glomerular filtration rate and lymphopenia in patients with migraine features, associated with a more severe course in this study, and lower CRP levels, linked to the phenotype with TTH features." (PMID 33391152, 2020). "The presence of lymphopenia and elevations of CRP and LDH may be helpful in the risk stratification of these patients." (PMID 33042695, 2020). "A plausible explanation is that an elevated mGPS may reflect compromised cell-mediated immunity as C-reactive protein is associated with lymphopenia and an impaired T-lymphocytic response in patients with colorectal tumours." (PMID 19319134, 2009). "Furthermore, elevated CRP levels are linked with lymphopenia and impaired T-cell responses in tumors, which might further promote cancer progression." (PMID 36875097, 2023). "The other population-based retrospective study showed that lymphopenia was associated with increased all-cause mortality risk, which was particularly evident in individuals with elevated C-reactive protein and/or RDW, a parameter of bone marrow dysregulation that may reflect chronic inflammation." (PMID 34229668, 2021). "In addition, particular laboratory features have been associated with worse disease outcomes including lymphopenia and elevations in the levels of lactate dehydrogenase, D-dimer, creatine kinase, troponin, and inflammatory markers (C-reactive protein, ferritin, etc.)." (PMID 32802627, 2020). "Poor outcomes were associated with older age, SID, central nervous system (CNS) involvement, lymphopenia, and elevated CRP." (PMID 41485003, 2026). "Laboratory results showed lymphopenia, neutrophilia, hepatic cytolysis and cholestasis, and a C-reactive protein level of 78 mg/L." (PMID 42221449, 2026).
lymphopenia (continued). "Laboratory findings were mainly elevated CRP (84.4%), lymphopenia (64.44%), elevated hs-cTni (51.11%), elevated N-terminal pro-B-type natriuretic peptide (NT-proBNP) (37.78%), decreased PaO2 (88.89%), and elevated PaCO2 (44.44%)." (PMID 41659953, 2026). "Lymphopenia and elevated levels of D-dimer, ferritin, IL-6, CRP, and procalcitonin were significantly higher in patients with stage 3 AKI than in patients with other AKI stages and the non-AKI group." (PMID 41598421, 2026). "In infants aged 28 to 32 gestational weeks, persistent thrombocytopenia, lymphopenia at 72 hours, and elevated CRP levels 48 hours after the onset of NEC are indicative of the need for surgical intervention." (PMID 39826099, 2025). "One year later, the patient was hospitalized with a right pleural effusion, elevated C-reactive protein, persistent lymphopenia, and positive rheumatoid factor." (PMID 40847225, 2025). "Participants in this study had some persistent laboratory abnormalities including lymphopenia (17.8%) and raised C-reactive protein (CRP) (8.5%)." (PMID 39820631, 2025). "These included lymphopenia and elevated inflammatory markers such as C-reactive protein (CRP), lactate dehydrogenase (LDH), ferritin, D-dimer, and interleukin-6 (IL-6)." (PMID 40731812, 2025). "The laboratory findings included a leukocyte count of 4.3 × 103/μL, which indicated lymphopenia at 1.26 × 103/μL, and a C-reactive protein (CRP) level below 0.5 mg/dL." (PMID 40710034, 2025). "Laboratory findings revealed neutropenia in 80% (116 cases), lymphopenia in 33% (48 cases), and an elevated C-reactive protein (CRP) in 79% (114 cases) of the patients." (PMID 40416099, 2025). "Such conditions were linked to increased disease severity, with elevated levels of inflammatory biomarkers (D-dimer, C-reactive protein), neutrophilia, and lymphopenia." (PMID 40862415, 2025). "The hematological (lymphopenia) and biochemical parameter variations (CRP and aminotransferase elevation) are less marked in African tick-bite fever than in Mediterranean spotted fever." (PMID 41244315, 2025). "The correlations with the extent of lung involvement were as follows:consolidation (p = 0.013); lymphopenia (p =0.054); C-reactive protein (p = 0.062); and LDH (p= 0.226)." (PMID 41523926, 2025). "Laboratory findings included lymphopenia and elevated levels of inflammatorymarkers (C-reactive protein, LDH, and D-dimer)." (PMID 41523926, 2025). "Laboratory tests showed elevated white blood cell count (WBC) of 24.5 with lymphopenia (0.9) and C-reactive protein (CRP) level of 136.5." (PMID 40574811, 2025). "The white blood cell count showed lymphopenia, and the C reactive protein and alanine aminotransferase levels were mildly elevated." (PMID 41244315, 2025). "Laboratory results indicated elevated levels of C-reactive protein (121.1 mg/L), creatinine (111 μmol/L), total bilirubin (22.8 μmol/L), interleukin-6 (26.2 pg/mL), and mild lymphopenia (280 cells/μL)." (PMID 40430794, 2025). "A complete blood count (CBC) showed lymphopenia (800/mm3), aneosinophilia and thrombocytopenia (108,000/mm3), moderate inflammatory syndrome (CRP = 4 mg/dL) and a biochemically moderate ALT elevation (ALT = 140 U/L)." (PMID 40126322, 2025). "As regards laboratory findings, lymphopenia present in 78/142 (55%) of the cohort and high inflammatory markers were evident as follows; high CRP 133/142 (93.6%), Hyperferritinemia 123/142 (86.6%) and high D-Dimer 122/142 (86%)." (PMID 41291581, 2025). "It is believed that, in comparison to low albumin, lymphopenia can be accepted as an indicator of malnutrition that is unaffected by elevated CRP." (PMID 40507738, 2025). "The CBC upon admission revealed lymphopenia (500/mm3), aneosinophilia and thrombocytopenia (113,000/mm3), inflammatory syndrome (CRP = 15 mg/dL) and muscle cytolysis syndrome (creatine kinase = 436 U/L, LDH = 256 U/L)." (PMID 40126322, 2025).
lymphopenia (continued). "Laboratory abnormalities such as lymphopenia, thrombocytopenia, hypoalbuminemia, and raised creatinine, urea, transaminases, and CRP were significantly more common." (PMID 40699520, 2025). "The laboratory findings most consistent with COVID-19 are lymphopenia, elevated CRP, D-dimer, and lactate dehydrogenase (LDH)." (PMID 40978879, 2025). "Laboratory tests revealed mild eosinophilia and lymphopenia, elevated lactate dehydrogenase, and normal C-reactive protein levels." (PMID 40847225, 2025). "Of those with COVID-19 disease, 88.6% had lymphopenia (0.99 [0.42–1.47], n = 47] and 66% had an elevated C-reactive protein (137, n = 35)." (PMID 40641657, 2025). "The laboratory tests revealed a normal white blood cell count (7,900/μL) with neutrophil predominance and lymphopenia (870/μL), an elevated C-reactive protein (CRP) level (6.25 mg/dL), and normal renal and hepatic function." (PMID 41141116, 2025). "Laboratory investigations revealed normocytic anemia (Hb 92 g/L, MCV 81.8 fL), leukopenia (2.9 × 109/L) with marked lymphopenia (Ly 0.4 × 109/L), elevated C-reactive protein (CRP 51.7 mg/L; n.v 0–5 mg/L) and ferritin (1262 μg/mL; n.v 22–275 μg/mL)." (PMID 40508215, 2025). "Given the patient’s bilateral opacities on CXR with elevated C-reactive protein (CRP), lymphopenia, elevated ferritin, and creatine phosphokinase (CPK), there was a high suspicion for COVID-19 pneumonia." (PMID 40656321, 2025). "Blood tests were also repeated, which showed an improvement in CRP (from 69 mg/L to 25 mg/L) and resolution of the leukopenia, lymphopenia, and liver function derangement observed prior to discharge." (PMID 41040775, 2025). "Regarding hematologic and biochemistry parameters, both groups had lymphopenia and an increase in CRP, but the differences were insignificant." (PMID 38994357, 2024). "In terms of laboratory markers, our study found that individuals with high viral loads showed significant elevations in markers such as CRP, D-dimer, lymphopenia, LDH, and cardiac markers, as well as low Ct levels." (PMID 39119409, 2024). "CSs is considered positive if there is lymphopenia and at least two other inflammatory markers of either: serum levels of ferritin, D-dimer, CRP, or LDH, are elevated." (PMID 38376738, 2024). "A total of 30.9% (69/223) of patients developed lymphopenia (lymphocyte count <1.0 × 109/L) and 20.6% (46/223) of them had an elevated C-reactive protein (CRP) level." (PMID 38400036, 2024). "Co-infected patients show lymphocytopenia and higher neutrophil levels, CRP, transaminases, and D-dimer levels." (PMID 38793006, 2024). "Laboratory evaluation showed lymphopenia (0.44 × 109/L, normal values 1.00–3.50 × 109/L) and a C-reactive protein level of 17 mg/L (normal values <5 mg/L)." (PMID 38813383, 2024). "Elevated CRP levels and lymphopenia observed in the early postoperative period are valuable indicators of infection." (PMID 39682623, 2024). "Co-infected patients exhibit more pronounced lymphocytopenia and higher levels of neutrophils, C-reactive protein, transaminases, D-dimer levels, and a higher chest CT involvement score." (PMID 38793006, 2024). "Subgroup analysis was conducted for supplemental oxygen use, high-dose corticosteroid administration, evidence of lymphopenia, C-reactive protein concentration, and total serum vitamin D concentration." (PMID 38383361, 2024). "This patient exhibited severe lymphopenia, increased CRP (14 mg/dL), hyperglycaemia and high levels of serum D‐dimers (>20 μg/mL)." (PMID 38501860, 2024). "Common findings include lymphopenia, neutrophilia, elevated levels of C-reactive protein (CRP), erythrocyte sedimentation rate (ESR), D-dimers, procalcitonin, fibrinogen, and ferritin, all correlating with disease severity." (PMID 39872865, 2024). "Regarding blood tests, severe cases showed lymphopenia, hypoalbuminemia, and lower haematocrit levels, whereas creatinine, urea, and C-reactive protein (CRP) levels were higher (4.7 vs. 12.3, p < 0.001)." (PMID 38475703, 2024).